FOXQ1 (forkhead box Q1)
Diseases named in the same sentence as FOXQ1 in open-access papers (continued):
Sharing a sentence is not in itself a finding about the gene and the disease.
gastric tumors (1 paper, 2017). "With respect to theimportant role of FOXQ1 in gastric development,we investigated its role in gastric tumorigenesis.We show that its up-regulation is associated withhigh-grade gastric tumors, thus indicating thatabundance of its encoded protein may aid gastriccancer progression." (PMID 28580309, 2017).
Impaired glucose tolerance (1 paper, 2022). An abnormal resistance to glucose, i.e., a reduction in the ability to maintain glucose levels in the blood stream within normal limits following oral or intravenous administration of glucose. "Notably, the deficiency of hepatic FOXQ1 causes increased blood glucose levels and impaired glucose tolerance, which may contribute to the development of T2DM." (PMID 36050744, 2022).
Insulin resistance (1 paper, 2020). Increased resistance towards insulin, that is, diminished effectiveness of insulin in reducing blood glucose levels. "Among the top downregulated genes, we identified Foxq1, an established repressor of FOXO1, confirming the presence of insulin resistance in which FOXO1 is hyperactive." (PMID 33345777, 2020).
mastocytosis (1 paper, 2023). A clonal myeloproliferative neoplasm characterized by the proliferation and accumulation of neoplastic mast cells in one or multiple organs or organ systems. "The identification of three oncogenes differentially methylated in mastocytosis patients, i.e., FOXQ1, pro, and ERG, was an interesting finding." (PMID 37762215, 2023). "Further studies on the relevance of oncogenes FOXQ1, TWIST1, and ERG as second-hit mutations in mastocytosis and novel therapeutic targets are needed." (PMID 37762215, 2023). "Importantly, three oncogenes—FOXQ1, TWIST1, and ERG—were identified as differentially methylated in mastocytosis patients, for the first time." (PMID 37762215, 2023).
metastatic cancers (1 paper, 2025). A carcinoma which has spread from the original site of growth to another anatomic site. "Unravelling the functions of FOXQ1 has the potential to facilitate the development of targeted treatments for metastatic cancers." (PMID 39777582, 2025).
Myocardial fibrosis (1 paper, 2023). "HFH1 (7.2-fold enrichment, p = 6.31 × 10−5, B–H p = 0.05), also known as FOXQ1, is involved in cell proliferation, differentiation, and myocardial fibrosis, though it has mainly been studied in cancer." (PMID 37840956, 2023).
Parkinson disease (1 paper, 2023). A progressive degenerative disorder of the central nervous system characterized by loss of dopamine producing neurons in the substantia nigra and the presence of Lewy bodies in the substantia nigra and locus coeruleus. "Moreover, plasma MALAT1, miR-125b, FOXQ1, PTGS2, and CDK5 could distinguish AD patients from controls, while only plasma MALAT1, miR-125b, and PTGS2 could discriminate AD patients from Parkinson’s disease patients." (PMID 36947499, 2023).
prostate adenocarcinoma (1 paper, 2022). "FOXQ1 expression was correlated with good DSS of tumor patients in kidney renal clear cell carcinoma and prostate adenocarcinoma and associated with poor DSS in liver hepatocellular carcinoma." (PMID 36118871, 2022). "FOXQ1 expression activated the following pathways in prostate adenocarcinoma: the IL6/JAK/STAT3 signaling pathway, interferon–alpha response pathway, UV response pathway, apoptosis pathway, and allograft rejection pathway." (PMID 36118871, 2022).
rectal cancer (1 paper, 2019). A primary or metastatic malignant neoplasm that affects the rectum. "This led to the identification of genes with increased H3K27ac, i.e., RIPK2, FOXQ1, KRT23, and EPHX4, which were also highly upregulated in primary rectal cancer in an independent dataset." (PMID 31404997, 2019).
uterine carcinosarcoma (1 paper, 2022). A usually aggressive malignant neoplasm arising from the uterine corpus and less often the cervix. "FOXQ1 also activated the following pathways in uterine carcinosarcoma: the androgen response pathway, IL6/JAK/STAT3 signaling pathway, interferon–alpha response pathway, adipogenesis pathway, and allograft rejection pathway." (PMID 36118871, 2022).
tumor (90 papers, 2012 to 2025). "In cancer, the upregulation of FOXQ1 is associated with significantly worse survival due to its ability to promote epithelial-to-mesenchymal transition, thereby allowing tumor cells to metastasize." (PMID 40522948, 2025). "Tumor-associated macrophages (TAMs) can induce EMT by regulating the JAK2/STAT3/miR-506-3p/FoxQ1 axis to enhance CRC migration and invasion." (PMID 38213716, 2024). "Both tumor-associated fibroblasts and macrophages have been found to increase the expression of FOXQ1 in cancer cells." (PMID 36319643, 2022). "Our study is the first to explore the association of FOXQ1 expression with tumor immunity from different perspectives." (PMID 36118871, 2022). "The relationship between FOXQ1 expression and cancer-related pathway activation was examined to explore the mechanism underlying its regulation of tumor progression." (PMID 36118871, 2022). "Recent research shows that regulatory mechanisms of CTC-mediated tumor metastasis involve Tumor-Associated Macrophages (TAMs) by regulating the JAK2/STAT3/miR-506-3p/FoxQ1 axis." (PMID 32429087, 2020). "However, FOXQ1 can apparently also function as a tumour suppressor in some types of cancer, and its loss in these cancers contributes to a worse prognosis." (PMID 39777582, 2025). "Versican V1 overexpression regulates FOXQ1 and induces tumor cells to secrete chemokine ligand 2, which is able to increase the numbers of tumor-associated macrophages, whereas the inhibition of versican V1 can significantly inhibit FOXQ1 expression." (PMID 36118871, 2022). "Moreover, FOXQ1 expression was closely related to the tumor mutational burden in 14 tumor types and microsatellite instability (MSI) in 8 tumor types." (PMID 36118871, 2022). "Taken together, these studies suggest that FOXQ1 levels in cancer may at least partially be controlled by the tumour-associated stroma, and that FOXQ1-dependent gene regulation in turn shapes the tumour microenvironment, which is supported by in silico analyses of public cancer data." (PMID 39777582, 2025). "FOXQ1 has emerged as a major regulator of epithelial-to-mesenchymal transition and tumour metastasis in cancers, especially carcinomas of the digestive tract." (PMID 39777582, 2025). "TGF-β induces the expression of FOXQ1, inducing the tumor characteristic in CRC cells by modulating the Wnt/β-catenin pathway." (PMID 41347087, 2025). "Several recent studies have outlined key mechanisms by which FOXQ1 drives EMT and tumour metastasis and have identified important regulators that control FOXQ1 levels and FOXQ1-dependent gene transcription." (PMID 39777582, 2025). "miR-378a acts as an inhibitor by preventing the abnormal activation of FOXQ1-cMYC axis signaling to improve the tumor characteristics of CRC." (PMID 41347087, 2025). "It is increasingly clear that the transcription factor FOXQ1 contributes to tumour progression and dissemination in several types of cancer, especially carcinomas of the gastrointestinal tract." (PMID 39777582, 2025). "We further identified upregulated transcription factors in these specific fibroblast subpopulations through transcription factor analysis, such as FOXF1 (a tumor suppressor transcription factor) and FOXQ1 (a tumor-promoting transcription factor)." (PMID 39963672, 2025). "FOXQ1 overexpression in PC stem-like cells and inhibition of FOXQ1 attenuates tumor formation, growth, and so on." (PMID 41347087, 2025).
tumor (continued). "FOXQ1 expression was increased in tumor tissue (61.3% high expression and 38.7% low expression) compared with paired adjacent tissue (37.8% high expression and 62.2% low expression) (P < 0.001)." (PMID 41347087, 2025). "FOXQ1’s abnormal upregulation of expression in human ESCC cells and knockdown of FOXQ1 can restrain the tumor characteristics of different ESCC cells in a mouse xenograft model in vivo." (PMID 41347087, 2025). "In OC, members such as FOXA1, FOXM1, FOXP4, FOXQ1, and FOXR2 primarily exhibit oncogenic functions, whereas others like FOXO and FOXP1 are associated with tumor-suppressive effects." (PMID 40746724, 2025). "This raises the intriguing possibility that FGF and TGF-β cooperate in inducing FOXQ1 expression and thereby promote tumour progression." (PMID 39777582, 2025). "Are there any common (epigenetic) mechanisms that drive its induction, and how does the tumour microenvironment contribute to the expression of FOXQ1?" (PMID 39777582, 2025). "In neoplastic conditions, FOXQ1 plays a role of promoter of tumor progression and has been involved in the regulation of invasion, EMT and apoptosis." (PMID 40176914, 2025). "While many of the factors that affect the abundance and activity of FOXQ1 can be explained by genetic or epigenetic changes in cancer cells, there is also some evidence that the tumour microenvironment contributes to the regulation of FOXQ1 levels." (PMID 39777582, 2025). "Having discussed how FOXQ1 controls gene expression in cancers, another relevant question to address is how the abundance of FOXQ1 itself is controlled in tumour cells." (PMID 39777582, 2025). "We found that FOXA1 and FOXM1 were significantly positively correlated with tumor purity in patients with BRCA, while FOXC2, FOXO3, FOXP1, and FOXQ1 were significantly negatively correlated with tumor purity in patients with BRCA." (PMID 38608123, 2024). "The forkhead box family transcription factor FOXQ1 is highly induced in several types of carcinomas, where it promotes epithelial-to-mesenchymal transition and tumor metastasis." (PMID 38432629, 2024). "FOXQ1 functions as a transcription factor in tumors and regulates multiple stages of tumor development, including the tumor invasion and metastasis, cell proliferation and angiogenesis." (PMID 38839744, 2024). "It has been reported that noncoding RNAs such as miR-124, miR-422a, and miR-1271 can promote tumor proliferation, migration and invasion by regulating the expression of FOXQ1." (PMID 38839744, 2024). "FOXQ1 promotes tumor metastasis in CRC by inducing epithelial–mesenchymal transition (EMT) in cancer cells and can exacerbate cancer by activating the oncogenic Wnt/β-catenin signaling pathway." (PMID 39456726, 2024). "CAFs induce FOXQ1 expression, leading to the activation of the FOXQ1/NDRG1 axis in tumor cells to enhance HCC initiation." (PMID 39085965, 2024). "In the current work, we explored the role and mechanism of EMT-related gene FOXQ1 in the proliferation, tumor stemness, invasion, and metastasis in PC." (PMID 37875474, 2023). "FOXQ1 overexpression promoted aerobic glycolysis and enhanced PC cell proliferation, tumor stemness, invasion, and metastasis." (PMID 37875474, 2023). "We also performed a suspension sphere-formation assay to determine FOXQ1’s contribution to tumor stemness and found that the FOXQ1 silencing groups exhibited decreased sphere formation efficiency." (PMID 37875474, 2023). "GEPIA assessment of the correlation between expression of the 15 differentially expressed FOXs (DE-FOXs) in the TCGA PAAD data set and the pathological stage of PAAD patients revealed a significant association between FOXK1, FOXQ1, and FOXP1 and tumor stages." (PMID 36622275, 2023). "To determine if FOXQ1 has contributed to the malignant activity of PC in vivo, we generated subcutaneous tumor nude mouse models." (PMID 37875474, 2023). "We also confirmed endogenous interaction between FOXQ1 and RbBP5 in various tumor types, including TNBC." (PMID 36319643, 2022).
tumor (continued). "We also analyzed the correlation of FOXQ1 expression with prognostic and clinicopathological parameters in 33 tumor types." (PMID 36118871, 2022). "Researchers have confirmed that versican V1, which promotes tumor cell metastasis and macrophage recruitment, is a direct transcriptional target of FOXQ1." (PMID 36118871, 2022). "Additional findings also revealed a positive feedback loop between CAFs and the FOXQ1/NDRG1 axis that drives the initiation of HCC in tumour cells." (PMID 36195857, 2022). "In contrast, mice implanted with mutant HMLER/FOXQ1-A129S or HMLER/FOXQ1-I132S had a median tumor onset on day 42 or 57, suggesting a significant delay in tumor initiation." (PMID 36319643, 2022). "Further study is needed to validate this regulatory axis in tumor samples and to characterize the redundant and distinct biological functions of FOXQ1 and SNAI1 in cancer and normal physiology." (PMID 36713812, 2022). "Subsequently, it was revealed that FOXQ1 knockdown led to inhibition of tumor sphere growth as well as down-regulated expression of stemness markers (CD133, SOX2 and OCT4) in HCT116R cells, whereas FOXQ1 overexpression led to the opposite in HT29R cells." (PMID 35183223, 2022). "It is found that FOXQ1 is over expressed in tumor tissues of CRC and its high expression is significantly related to the stage and lymph node metastasis of CRC." (PMID 35114976, 2022). "Through plotting the tumor growth curves, we found that tumors’ volume in the Foxq1-overexpressing group was significantly higher than that in the control group." (PMID 33875643, 2021). "Consistent with the Foxq1 tumor-promoting effects, qRT-PCR and western blot showed that the expression of related genes in the tumors were also dramatically increased in Foxq1-overexpressing group compared to those in the control group." (PMID 33875643, 2021). "In contrast, its ectopic upregulation significantly suppresses cell proliferation, colony formation, and invasion by targeting Forkhead box Q1 (FOXQ1), which is involved in tumor cell proliferation and metastasis." (PMID 35201458, 2021). "FOXQ1 is a transcription factor involved in the EMT, which is associated with tumor growth and metastasis." (PMID 34922601, 2021). "Overexpression of FOXQ1 has been linked to EMT and tumor metastasis in various cancers, and thus it is of interest to determine its molecular functions." (PMID 34298659, 2021). "In situ hybridization in primary healthy and tumor colon tissues confirmed that FOXQ1 gene expression is restricted to the CRC sections that express YAP in the nucleus." (PMID 33879786, 2021). "Results showed that LINC00667 and FOXQ1 were down-regulated, whereas miR-4319 level was enhanced in tumor tissues from sh-LINC00667 group compared with those from sh-NC group." (PMID 33569351, 2020). "The effect of FOXQ1 knockdown was further confirmed in in vivo experiments, demonstrating that FOXQ1 inhibition in CRC cells results in slower xenograft tumor growth and angiogenesis." (PMID 33330033, 2020). "TAMs can promote CRC migration, invasion, and circulating tumor cell (CTC)-mediated metastasis via the JAK2/STAT3/miR-506-3p/FoxQ1 axis, enhancing macrophage recruitment through the production of CCL2 by tumor cells." (PMID 32943996, 2020). "To dissect the impact that FOXQ1 had on tumor progression and malignancy, we appraised its influence on cell proliferation and migration." (PMID 33330033, 2020). "SR9243 also upregulated or downregulated genes associated with tumour proliferation, apoptosis, angiogenesis, invasion and migration, such as ANGPTL4, PDGFR, DUSP5, MMP7, FOXQ1 and MXD1 26–31." (PMID 31138790, 2019). "In contrast, FOXQ1 knockdown in miR-4319-suppressive Hep3B cells partly ceased the potency of anti-miR-4319 on tumour cell proliferation, colony formation, apoptosis, invasion and cancer stem traits (P<0.05)." (PMID 31853229, 2019).
tumor (continued). "Our recent studies showed that the miR-216 family and miR-217 were downregulated in PDAC tissues and that these miRNAs acted as anti-tumor miRNAs by targeting FOXQ1 and ANLN, respectively." (PMID 29988949, 2018). "The mean tumor volume and weight of the FOXQ1 silencing vector-expressing EC109 and EC9706 xenografts grew at a slower rate than those derived from the xenografts expressing control vector." (PMID 28726780, 2017). "We observed that decreased expression of FoxQ1 enhanced the sensitivity of four typical chemotherapeutic agents and inhibited tumor growth in nude mice when combined with cisplatin." (PMID 25356753, 2014). "Microarray and qRT-PCR analysis of laser-dissected CRC biopsies showed that FOXQ1 was significantly overexpressed in tumor epithelium and reactive stroma tissue." (PMID 23555880, 2013). "Positive staining for FoxQ1 was mainly localized to tumour cells and pneumocytes in the cytoplasm and plasmalemma at different levels." (PMID 22761930, 2012). "High expression of FoxQ1 was detectable in TMAs of tumour samples and was significantly correlated with decreased overall survival." (PMID 22761930, 2012). "Overexpression of FOXQ1 in CRC has been shown to enhance tumor growth." (PMID 40722723, 2025). "Consequently, EGFR inhibition counteracted FOXQ1-dependent tumour growth, vascularisation, and metastasis in mouse xenograft assays, and this beneficial effect was further enhanced by co-treatment with the VEGF receptor inhibitor sunitinib." (PMID 39777582, 2025). "Forkhead box Q1 (FoxQ1) is a major regulator of tumor metastasis." (PMID 41341593, 2025). "In light of evidence from preclinical studies, this may be sufficient to render FOXQ1 dysfunctional and thereby prevent tumour progression." (PMID 39777582, 2025). "Forkhead box Q1 (FOXQ1) is a member of the Forkhead box gene family and an important transcription factor closely associated with several human diseases, especially tumorigenesis and tumor progression." (PMID 41347087, 2025). "As discussed in the preceding sections, FOXQ1 is involved in EMT and metastasis in several types of cancer, and there is mounting evidence from preclinical models that interfering with FOXQ1-mediated functions in cancer cells can slow down or even reverse tumour progression." (PMID 39777582, 2025). "Additionally, the expression levels of FOXP3, FOXO3, FOXO1, FOXA2, and FOXM1 were found to be elevated in GBM tissues from the TCGA database compared to non-tumor brain tissues, while the level of FOXQ1 was reduced." (PMID 38561331, 2024). "Several regulatory mechanisms of FOXQ1 in normal and tumor cells have been reported." (PMID 38839744, 2024). "MiR-937 inhibited tumor development through FOXQ1 targeting." (PMID 37689738, 2023). "FOXQ1 induces tumor angiogenesis, cell proliferation, resistance to chemotherapy, and EMT." (PMID 37689738, 2023). "Additionally, our findings demonstrated that elevated FOXQ1 expression boosts PC cell proliferation, tumor stemness, invasion, and metastasis both in vitro and in vivo." (PMID 37875474, 2023). "Immuno-morphometry revealed that 30–40% of the tumor cells expressed FOXQ1, MMP11, and THBS2." (PMID 38156105, 2023). "The results showed that PC tumor tissues had higher FOXQ1 levels than nearby non-tumor tissues." (PMID 37875474, 2023). "FOXQ1 mRNA was more abundant in 73.33% of PC samples in comparison with non-tumor samples." (PMID 37875474, 2023). "FOXQ1 upregulation could initiate HCC by enhancing the communication between cancer association fibroblasts (CAF) and tumor cells." (PMID 35255005, 2022). "The evidence indicates a correlation of FOXQ1 with tumor progression, and a deepening of our understanding of FOXQ1 could provide important clues for research into pathogenic tumor mechanisms." (PMID 36118871, 2022). "FOXQ1 expression also regulates the progression of different tumor types." (PMID 36118871, 2022). "FOXQ1 can regulate the immune response and influence tumor progression." (PMID 36118871, 2022).